CTNND1 (catenin delta 1)
Description:
Key regulator of cell-cell adhesion that associates with and regulates the cell adhesion properties of both C-, E- and N-cadherins, being critical for their surface stability. Promotes localization and retention of DSG3 at cell-cell junctions, via its interaction with DSG3. Beside cell-cell adhesion, regulates gene transcription through several transcription factors including ZBTB33/Kaiso2 and GLIS2, and the activity of Rho family GTPases and downstream cytoskeletal dynamics. Implicated both in cell transformation by SRC and in ligand-induced receptor signaling through the EGF, PDGF, CSF-1 and ERBB2 receptors.
Synonyms: CAS; p120(ctn); KIAA0384; p120; p120cas; p120ctn; BCDS2; CTNND; p120(CAS)
Tractability: Antibody: UniProt places it where antibodies can reach, with high confidence; its Gene Ontology location is reachable by antibodies, with high confidence; the Human Protein Atlas places it where antibodies can reach. PROTAC: UniProt records ubiquitination sites on it; ubiquitination databases record sites on it; its protein half-life has been measured.
Gene: Protein-coding gene on chromosome 11 (57,753,243 to 57,819,546, forward strand). Ensembl gene ENSG00000198561.
Subcellular location: Cell junction, adherens junction; Cytoplasm; Nucleus; Cell membrane; Cell junction; Nucleus (Isoform 1A); Nucleus (Isoform 2A); Nucleus (Isoform 3A); Cytoplasm (Isoform 4A); Cytoplasm (Isoform 1AB)
Subcellular location (Human Protein Atlas): Plasma membrane; Basal body
Pathways (Reactome):
Cell-Cell communication: Activation of STAT3 by cadherin engagement; Adherens junctions interactions; CDH11 homotypic and heterotypic interactions; Degradation of CDH1; Regulation of CDH1 Function; Regulation of CDH11 function; Regulation of CDH19 Expression and Function; SRC activates STAT3 in a quantitative manner, through Cadherin-11 (CDH11), RAC1 and gp130 (IL6ST)
Disease: InlA-mediated entry of Listeria monocytogenes into host cells
Signal Transduction: VEGFR2 mediated vascular permeability
Gene Ontology:
Molecular function: cadherin binding; phosphatase binding; phosphatase inhibitor activity; protein binding; protein sequestering activity; signaling receptor binding; cell-cell adhesion mediator activity
Biological process: cell-cell adhesion mediated by cadherin; negative regulation of blood vessel branching; negative regulation of D-glucose transmembrane transport; negative regulation of intracellular signal transduction; negative regulation of transcription by RNA polymerase II; positive regulation of protein localization to cell-cell junction; protein stabilization; regulation of postsynaptic membrane neurotransmitter receptor levels; cell migration involved in sprouting angiogenesis; cell-cell adhesion
Cellular component: adherens junction; anchoring junction; catenin complex; cell-cell junction; cytoplasm; cytosol; extracellular exosome; midbody; nucleus; plasma membrane
Genetic constraint (gnomAD): Loss-of-function variants: 10 observed, 90.87 expected, observed/expected ratio (o/e) 0.11, 90% interval 0.067 to 0.19. The upper end of that interval is the gene's LOEUF score, 0.19, which puts it in group 1 of 6, group 1 being the genes least tolerant of losing a copy. Missense variants: 943 observed, 1,202.7 expected, observed/expected ratio (o/e) 0.78, 90% interval 0.74 to 0.83. Synonymous variants: 403 observed, 433.74 expected, observed/expected ratio (o/e) 0.93, 90% interval 0.86 to 1.01.
Gene-disease validity (ClinGen):
ClinGen rates the evidence that CTNND1 causes each of these diseases.
blepharocheilodontic syndrome 2 (autosomal dominant): Definitive.
Homologues: Orthologues: macaque CTNND1 (99% identical), chimpanzee CTNND1 (99% identical), rat Ctnnd1 (98% identical), mouse Ctnnd1 (97% identical), rabbit CTNND1 (97% identical), dog CTNND1 (97% identical), guinea pig CTNND1 (96% identical), pig CTNND1 (91% identical), zebrafish ctnnd1 (58% identical), tropical clawed frog ctnnd1 (47% identical), Drosophila melanogaster p120ctn (26% identical), Caenorhabditis elegans jac-1 (26% identical). Paralogues in human: ARVCF (46% identical), CTNND2 (36% identical), PKP4 (34% identical), PKP2 (20% identical), PKP3 (20% identical), PKP1 (19% identical).
Diseases named in the same sentence as CTNND1 in open-access papers:
CTNND1 is named in the same sentence as 95 diseases in open-access papers, as found by Europe PMC text mining. Sharing a sentence is not in itself a finding about the gene and the disease. The quoted sentences say what the papers report.
breast carcinoma (29 papers, 2015 to 2025). "We therefore subsequently examined the N-terminus of CTNND1 transcripts in more detail in mRNA samples of a cohort of 96 breast cancer patients using variant-encompassing primers spanning the 5’ region containing the alternative entry points." (PMID 31569498, 2019). "Consistently, the increased cytoplasmic localization of CTNND1 is closely associated with the increased invasive phenotype of E-cadherin-deficient breast cancer cells." (PMID 29228664, 2017). "Catenin delta-1 (CTNND1) functions as an oncogene and is known to be the driver of metastatic cancer progression in hepatocellular carcinoma, breast cancer, and colorectal cancer." (PMID 37218885, 2023). "Decreased CTNND1 is a crucial intrinsic contributor to homing to the bones and the survival of the breast cancer cells in the bone microenvironment." (PMID 34830862, 2021). "Of note, expression of just one of these basal B-specific splice variants, which are CTNND1, ENAH and PLOD2, is sufficient to lower the disease-specific survival rate of basal B-like breast cancer patients compared to basal A-like." (PMID 33845831, 2021). "Our studies demonstrate that RORα2 positively regulates CTNND1 expression to increase cell motility and migration in breast cancer cells." (PMID 28931919, 2017). "Our data revealed an essential role for endogenous CTNND1 in MORC2-enhanced migration and invasion of E-cadherin-deficient MDA-MB-231 and Hs578T breast cancer cells." (PMID 29228664, 2017). "Given that CTNND1 is implicated in the metastatic progression of breast cancer and that MORC2 interacts with CTNND1, we next assessed the role of CTNND1 in MORC2-enhanced migration and invasion of breast cancer cells." (PMID 29228664, 2017). "In addition, in other epithelial cell carcinomas, such as gastric carcinoma, breast cancer and melanoma, patients in the CTNND1-high group also showed poor immunotherapeutic response than those in the CTNND1-low group." (PMID 38169514, 2024). "Previously, we identified CTNND1 as an RORα2-specific target gene in breast cancer cells." (PMID 32120841, 2020). "While retaining all beneficial features of RORα in breast cancer cells, our results propose that RORα2 and LSD1 may play crucial roles in tumorigenesis via elevating CTNND1 expression in human breast cancer." (PMID 28931919, 2017). "As MORC2 is predominately localized in the nuclear, we hypothesized that the involvement of MORC2-CTNND1 interaction in breast cancer progression is mainly mediated by nuclear CTNND1." (PMID 29228664, 2017). "Since decreased CTNND1 promoted the intrinsic malignancy of breast cancer cells and correlated more frequently with bone metastasis in breast cancer patients, we next explored whether CTNND1 plays a role in bone metastasis of breast cancer." (PMID 34830862, 2021). "Thus, whether the metastasis-promoting activity of MORC2 and the interaction between MORC2 and CTNND1 could apply to other breast cancer subtypes remain to be addressed in the future." (PMID 29228664, 2017). "Anti-p120-3 specifically detected p120-3 by Western blotting as shown using lysates of wild-type 4T1 murine mammary cancer cells and 4T1 p120 KO cells generated by CRISPR/Cas9-mediated knock-out of Ctnnd1." (PMID 30643202, 2019). "To address the molecular mechanisms by which MORC2 promotes breast cancer invasion and metastasis through its PRD domain, we further identified CTNND1 as a novel MORC2-binding partner by LC-MS/MS and biochemical analyses." (PMID 29228664, 2017). "Taken together, these results suggest that MORC2 promotes breast cancer invasion and metastasis through its PRD domain-mediated interaction with CTNND1." (PMID 29228664, 2017). "Findings presented here show that MORC2 promotes breast cancer invasion and metastasis, and the PRD domain is essential for the metastasis-promoting properties of MORC2 through interacting with CTNND1." (PMID 29228664, 2017).
breast carcinoma (continued). "Third, it identifies CTNND1 as a novel binding partner of MORC2, which is required for MORC2-mediated breast cancer migration and invasion." (PMID 29228664, 2017). "Together, although CTNND1 is recognized as a key regulator in cancer progression and metastasis, the mechanistic aspects of its prometastatic signaling in breast cancer are not fully characterized." (PMID 29228664, 2017). "However, the expression of CTNND1 had no prominent influence on either OS or DMFS in other types of breast cancer (Figure A1A)." (PMID 34830862, 2021). "Interestingly, protein abundance of HPRT1, HNRNPA0, IFIT3, CTNND1 and EIF4A3 predicted poor overall survival in breast cancer patients, however, PPM1A association was non-significant." (PMID 32532008, 2020).
lung carcinoma (14 papers, 2012 to 2025). "In previous studies, CTNND1 was documented to promote many types of human cancers, including hepatocellular carcinoma and lung cancer." (PMID 28694563, 2017).
colon carcinoma (13 papers, 2010 to 2024). "We found that in colon cancer cells, cortactin interacts with CTNND1, and that curcumin strongly decreased this association, likely due to diminished cortactin phosphorylation at Tyr421." (PMID 24465712, 2014). "Indeed, studies in breast and colon cancer indicate that cytosolic CTNND1 controls the invasive phenotype of E-cadherin-deficient tumor cells." (PMID 27193094, 2016). "In conclusion, we have shown that pTyr421-cortactin is overexpressed in colon cancer, that curcumin modulates the activity of PTPN1 phosphatase to decrease cortactin phosphorylation and interaction with CTNND1, and ultimately to decrease colon cancer cell migration." (PMID 24465712, 2014). "The AS of CALD1, COL6A3, FN1, MAST2, LGR5 and ITGB4 were previously validated in colon cancer using RT-PCR24, while CLSTN1, AUP1, CTNND1, CALD1 and COL6A3 were shown to exhibit tumour-specific splice variants in colon, bladder and prostate cancers." (PMID 28592875, 2017).
colorectal cancer (11 papers, 2010 to 2024). A primary or metastatic malignant neoplasm that affects the colon or rectum. "In colorectal cancer, miR-425-5p promotes cell proliferation, migration, invasion, and EMT by activating the CTNND1-mediated β-catenin pathway." (PMID 34686190, 2021). "miR-425-5p could increase tumor growth and metastasis via affecting CTNND1-mediated β-catenin pathway and EMT in colorectal cancer." (PMID 37497401, 2023). "For example, hsa-miR-425-5p may promote tumor occurrence and metastasis by activating CTNND1 related pathway, hsa-miR-186-5p regulates TGFβ signaling pathway through expression suppression of SMAD7 and SMAD6 genes in colorectal cancer." (PMID 36561136, 2022).
hepatocellular carcinoma (11 papers, 2016 to 2023). A malignant tumor that arises from hepatocytes. "For example, CTNND1 overexpression in primary liver cancer (hepatocellular carcinoma; HCC) promoted cancer phenotypes via Wnt/β-catenin axis activation." (PMID 34852711, 2022). "The article of Tang stated CTNND1 could elevate proliferation, migration, and invasion of hepatoma cells in vitro." (PMID 32760218, 2020). "However, the mechanism and clinical significance of CTNND1 deregulation in hepatocellular carcinoma (HCC) remains unknown." (PMID 27193094, 2016).
pancreatic cancer (9 papers, 2015 to 2025). "Furthermore, a switch from E-cadherin expression to P-cadherin, which is associated with a more invasive behavior, in ovarian and pancreatic cancer cell lines results in the translocation of CTNND1 to the cytosol, which in turn induces cell migration by activating RAC1 and CDC42." (PMID 27193094, 2016). "CTNNA1, CTNNB1, and CTNND1 are key molecules potentially involved in pancreatic cancer metastasis mediated by hsa-miR-30d-5p/GJA1." (PMID 36741258, 2023). "Predicted to be targeted by miR409, Catenin Delta 1 (CTNND1) along with Catenin alpha 1 (CTNNA1) and Catenin Beta 1 (CTNNB1) expression was shown to indicate a poor prognosis for pancreatic cancer patients." (PMID 36983764, 2023). "Moreover, survival analysis shows that pancreatic cancer patients with high expression of CTNNA1, CTNNB1, or CTNND1 have a poor prognosis." (PMID 36741258, 2023).
gastric cancer (7 papers, 2016 to 2024). A primary or metastatic malignant neoplasm involving the stomach. "The discovery of CTNND1 as a new hereditary gastric cancer gene would permit identifying high-risk individuals and establishing preventive measures, early diagnosis, and personalized treatments." (PMID 38796558, 2024). "Defects in CTNND1 could be involved in germline predisposition to gastric cancer by altering E-cadherin and, consequently, cell-to-cell interactions." (PMID 38796558, 2024). "The role of the CTNND1 gene in inherited gastric cancer predisposition is still unclear." (PMID 37686589, 2023). "The role of CTNND1 variants in inherited gastric cancer predisposition is still unclear." (PMID 37686589, 2023). "The expression of miR-145 is upregulated in gastric cancer, which inhibits the expression of catenin (cadherin-associated protein), delta 1 (CTNND1), and N-cadherin while promoting the translocation of CTNND1 and E-cadherin from the cytoplasm to the cell membrane." (PMID 27464701, 2016). "We identified four missense and two synonymous variants in the CTNND1 gene classified as variants of uncertain significance (VUS) following the ACMG guidelines, both in patients with diffuse and mixed gastric cancer subtypes." (PMID 37686589, 2023). "For example, miR-145 and miR-29c target CTNND1 and prevent metastatic phenotypes in gastric cancer cells." (PMID 31913290, 2020). "However, we identified six VUS in the CTNND1 gene, both in patients with diffuse and mixed gastric cancer subtypes." (PMID 37686589, 2023). "It has been reported previously that CTNND1, EZH2, BCL2L2, CDH2, VIM, and EGFR have positive correlation to proliferation, invasion, and poor prognosis of gastric cancer." (PMID 28694563, 2017).
glioma (6 papers, 2010 to 2026). A benign or malignant brain and spinal cord tumor that arises from glial cells (astrocytes, oligodendrocytes, ependymal cells). "Potential glioma risk genes with a pathogenic GV most frequently played roles in cell adhesion (CTNND1, EPCAM), immune response (IFIH1, SAMHD1), and ion transport (SLC4A7, TRPM1)." (PMID 41546701, 2026).
melanoma (6 papers, 2012 to 2025). A malignant, usually aggressive tumor composed of atypical, neoplastic melanocytes. "Given that FLG, PKP1, and TGM1 are ECM related, their association with CTNND1 raises the possibility that altered adhesion dynamics converge with ECM remodeling to promote melanoma progression." (PMID 41321310, 2025). "Our data underscores the palmitoylation of CTNND1 as a critical posttranslational modification in melanoma, with implications for understanding the molecular mechanisms underlying melanoma metastasis." (PMID 41321310, 2025). "Specifically, ZDHHC13 palmitoylates CTNND1, enhancing E-cadherin stability on the melanoma cell membrane." (PMID 41321310, 2025). "The interaction between ZDHHC13 and CTNND1 was further validated through coimmunoprecipitation experiments in SK-Mel-28 melanoma cells and HEK-293T cells." (PMID 41321310, 2025). "Immunofluorescence revealed CTNND1’s presence both on the cell membrane and in the cytosol of melanoma cell lines." (PMID 41321310, 2025). "Our findings demonstrate that S-palmitoylation is critical for CTNND1’s recruitment to the membrane and its interaction with E-cadherin, suggesting that CTNND1 palmitoylation regulates melanoma metastasis by modulating E-cadherin." (PMID 41321310, 2025). "Further validation in melanoma cells confirmed that ZDHHC13 is the primary PAT responsible for CTNND1 palmitoylation." (PMID 41321310, 2025). "To explore the mechanism of CTNND1 palmitoylation on melanoma metastasis, we conducted mass spectrometry screening for proteins interacting with WT and C618S CTNND1 in melanoma cells." (PMID 41321310, 2025). "To test this, we overexpressed ZDHHC13 in melanoma cells expressing either WT or C618S CTNND1 and conducted in vitro migration and invasion assays." (PMID 41321310, 2025). "E-cadherin knockdown in cells expressing WT CTNND1 also abrogated CTNND1’s ability to inhibit melanoma migration and invasion, indicating that CTNND1 palmitoylation mainly suppresses melanoma metastasis through E-cadherin in vitro." (PMID 41321310, 2025). "To investigate the impact of CTNND1 palmitoylation on melanoma metastasis, we generated melanoma cell lines expressing either WT CTNND1 or the palmitoylation-deficient C618S mutant." (PMID 41321310, 2025). "CTNND1 is a potential palmitoylated protein responsible for melanoma metastasis." (PMID 41321310, 2025). "CTNND1 palmitoylation delays melanoma metastasis to the lung." (PMID 41321310, 2025). "Significantly, ZDHHC13 failed to suppress lung colonization in immunodeficient mice with melanomas expressing C618S CTNND1, but was able to do so in immunocompetent C57BL/6J mice with the same C618S CTNND1–expressing tumors." (PMID 41321310, 2025). "Silencing ZDHHC17 or ZDHHC21, however, had no significant impact on CTNND1 palmitoylation or melanoma cell invasion." (PMID 41321310, 2025). "The results revealed that ZDHHC13 effectively suppressed metastasis in cells with WT CTNND1, but not in those with the C618S mutation, suggesting that ZDHHC13 suppresses melanoma metastasis primarily through CTNND1 palmitoylation in vitro." (PMID 41321310, 2025). "Importantly, our data show that concurrent activation of both downstream arms of ZDHHC13 signaling — enhanced CTNND1 palmitoylation and suppression of macrophage-derived MMP12 — produces the most robust inhibition of melanoma metastasis." (PMID 41321310, 2025).
blepharocheilodontic syndrome (4 papers, 2023 to 2026). An ectodermal dysplasia syndrome characterized by the association of abnormalities of the eyelids, lips, and teeth. "Other rare conditions in humans seen in combination with distichiasis are facial dermal dysplasia caused by a frameshift mutation in TWIST2 and Blepharocheilodontic syndrome linked to mutations in CTNND1 and CDH1 encoding proteins in the cadherin–catenin complex." (PMID 37488637, 2023). "CTNND1, seen in connection with "Blepharocheilodontic syndrome" with distichiasis in humans, is situated on CFA18 but more than 10 MB upstream from the top SNP on CFA18." (PMID 37488637, 2023). "CTNND1 mutations can lead to blepharocheilodontic syndrome (BCDS)." (PMID 37274823, 2023). "CTNND1 has previously been associated with some hereditary syndromes with birth defects, including blepharocheilodontic syndrome, nonsyndromic cleft lip with or without palate (CLP) and a craniofacial and cardiac syndrome." (PMID 38796558, 2024). "Notably, in humans, numerous mutations in genes encoding proteins of the adherens junction complex, including core components such as E-CADHERIN (CDH1) and P120-CATENIN (CTNND1), have been implicated in causing cleft lip as part of blepharocheilodontic syndrome and non-syndromic cleft lip." (PMID 41231213, 2026).